CAV1 (caveolin 1)
Diseases named in the same sentence as CAV1 in open-access papers (continued):
Sharing a sentence is not in itself a finding about the gene and the disease.
Impaired glucose tolerance (1 paper, 2020). An abnormal resistance to glucose, i.e., a reduction in the ability to maintain glucose levels in the blood stream within normal limits following oral or intravenous administration of glucose. "We observed that CAV1 KO mice were resistant to weight gain when on HFD, although they had high serum cholesterol and FFA levels, impaired glucose tolerance and were insulin resistant." (PMID 32718046, 2020).
inflammatory skin disorders (1 paper, 2019). "We provide an overview of the role of the caveolin-1 expression in different hyperproliferative and inflammatory skin diseases and discuss its possible active involvement in the therapeutic effects of different well-known drugs widely applied in dermatology." (PMID 31877626, 2019). "The effect of different drugs, which are applied for the treatment of various hyperproliferative and inflammatory skin disorders, can be also directly or indirectly connected with the manipulation of Cav-1 expression." (PMID 31877626, 2019). "Collectively, these results support the central role of Cav-1 in pathogenesis of different hyperproliferative and inflammatory skin disorders, as well as its possible role as a target for their regulation." (PMID 31877626, 2019).
iron metabolism disorder (1 paper, 2023). "In summary, HFD or PA + OA aggravated macrophage iron metabolism disorder by up-regulating the expression of Cav-1 and HO-1." (PMID 37941054, 2023). "The expression of Cav-1 was decreased in NAFLD hepatocytes (P < 0.05), accompanied by iron metabolism disorder." (PMID 37941054, 2023). "In macrophages, the up-regulation of Cav-1 promoted the expression of HO-1 in CD68+CD163+ macrophages, which facilitated the degradation of red blood cells into Fe2+ within macrophages and accelerated iron metabolism disorder in NAFLD." (PMID 37941054, 2023).
keratitis (1 paper, 2013). A corneal disease that is characterized by inflammation of the cornea. "Using a mouse keratitis model, caveolin-1-/- mice showed reduced entry of virus as compared to wild type mice and showed reduced levels of both pSrc and CXCL1 expression complimenting our in vitro data." (PMID 24147000, 2013).
keratoconus (1 paper, 2023). A degenerative, structural disorder of the eye, characterized by a cone-shaped protrusion of the cornea. "We overlaid these 4 modules with FRGs and found that 8 FRGs (LCE2C, NOS2, AKR1C3, CAV1, MMD, LINC00618, SNCA, SLC7A11) were closely related to the disease state of keratoconus." (PMID 37626095, 2023).
Klebsiella pneumonia (1 paper, 2022). An pneumonia caused by infection with Klebsiella. "CAV1 depletion reduced mouse survival rate, enhanced bacterial burdens, facilitated bacterial dissemination, and potentiated pro-inflammatory responses in mice infected with Klebsiella pneumonia." (PMID 36387401, 2022).
latent infection (1 paper, 2020). "Along with this finding, the multiple functions of Cav-1 with relevance to cell regulation can have important implications in HIV latent infection." (PMID 33121153, 2020). "One molecule that can be important in HIV latent infection is Caveolin 1 (Cav-1)." (PMID 33121153, 2020). "In lieu of this finding, the current review examines the potential role of Cav-1 in HIV latent infection and provides a perspective that helps uncover new insights to understand HIV latent infection." (PMID 33121153, 2020). "Since Cav-1 regulates cell cycle, signaling involving NCCLR can be important and play an essential role in promoting infected cells to become quiescent, subsequently resulting in latent infection as a cell survival mechanism." (PMID 33121153, 2020).
leukoaraiosis (1 paper, 2022). "After adjusting for potential confounders, increased hsa-miR-3074-3p [odds ratio (OR), 1.41; 95% confidence interval (CI), 1.17–1.69; P = 0.001] and reduced Cav-1 level (OR, 0.29; 95% CI, 0.16–0.53; P = 0.001) were also significantly associated with a higher risk of leukoaraiosis." (PMID 36357389, 2022). "In leukoaraiosis patients, human serum miR-3074-3p, which shared a conserved seed region with mouse miR-3074-1-3p, was increased while serum Cav-1 was decreased." (PMID 36357389, 2022). "Patients with leukoaraiosis were more likely to have a higher level of hsa-miR-3074-3p and a lower level of Cav-1 (both P = 0.001)." (PMID 36357389, 2022). "Compared to patients with mild leukoaraiosis, patients with severe leukoaraiosis tended to have a higher level of hsa-miR-3074-3p (P = 0.1309) but a lower level of Cav-1 (P = 0.0159)." (PMID 36357389, 2022). "In this study, we investigated the potential role of endothelial Cav-1 linking vasculature with ischemic demyelination in the mouse bilateral carotid artery stenosis (BCAS) model and leukoaraiosis patients." (PMID 36357389, 2022).
Listeria infection (1 paper, 2016). "Instead, analyses in Cav-1−/− mice showed that Cav-1 increased liver autophagy during Listeria infection." (PMID 27694929, 2016).
lung large cell neuroendocrine carcinomas (1 paper, 2015). "The findings of the present study are consistent with those of our previous study of differential Cav1 expression according to histotype, showing that all lung large cell neuroendocrine carcinomas and matched brain metastases were Cav1 negative." (PMID 26315660, 2015).
lymphoid tumor (1 paper, 2016). "Taken together, our preliminary data support a hypothesized role for CAV1 in lymphoid tumor progression, likely through an immune regulatory method." (PMID 28018857, 2016).
macular holes (1 paper, 2023). A hole in the macula of the retina. "Mean normalised Caveolin-1 concentration in PDR vitreous was 12.04 ng/mL (SD 2.31) vs. 7.36 ng/mL (SD 1.36) in macular hole vitreous." (PMID 36289445, 2023). "ELISA method analysed Caveolin-1 level from the vitreous fluid of 11 patients with PDR and 7 patients with macular hole." (PMID 36289445, 2023).
malignant glioma (1 paper, 2020). A grade III or grade IV glioma arising from the central nervous system. "The same study demonstrated that filipin treatment prevents caveolin-1 translocation to the nucleus and this was associated with significant radio-sensitisation of malignant glioma cells." (PMID 32824727, 2020).
malignant salivary gland tumors (1 paper, 2021). "In other studies, caveolin-1 expression was not correlated with the tumor size and stage in benign and malignant salivary gland tumors, suggesting that this protein may function as a tumor suppressor in these neoplasms; however, its clinical/prognostic implications are not yet clear." (PMID 33037799, 2021).
meningoencephalitis (1 paper, 2024). Inflammation of the meninges and brain, generally secondary to an infectious cause. "This study aims to investigate the regulatory role of Cav-1 in the pathogenesis of meningoencephalitis induced by A. cantonensis infection." (PMID 38922036, 2024). "The expression of the Cav-1 protein is positively correlated with brain edema, BBB permeability, and MMP-9 activity in infection-induced meningoencephalitis with A. cantonensis." (PMID 38922036, 2024). "The study evaluates the critical role of Cav-1 regulation through the TLR4/MyD88 signaling pathway, modulates tight junction proteins, influences BBB permeability, and contributes to brain damage in A. cantonensis-induced meningoencephalitis." (PMID 38922036, 2024).
metastatic colorectal cancer (1 paper, 2023). "In fibroblasts activated by exosomes from human primary and metastatic colorectal cancer cells, caveolin-1 (Cav-1) expression was significantly down-regulated and GLUT1, the rate-limiting transporter of glucose uptake, was significantly up-regulated." (PMID 37349803, 2023).
microcephaly (1 paper, 2018). A congenital or acquired developmental disorder in which the circumference of the head is smaller than normal for the person's age and sex. "However, it has been reported that BBB permeability, but not microcephaly or DHA deficiency, can be completely rescued in 2aKO mice by genetic deficiency of Caveolin-1 (Cav-1)." (PMID 30074985, 2018).
monoclonal gammopathy of undetermined significance (1 paper, 2025). "First, CAV1 expression was evaluated in plasma cells obtained from healthy donors (HD) and patients with monoclonal gammopathy of undetermined significance (MGUS) or MM." (PMID 39630017, 2025).
multiple myeloma (1 paper, 2011). "In multiple myeloma, proteasome inhibitors blocked VEGF-triggered CAV1 phosphorylation and expression resulting in reduced migration and survival." (PMID 21471610, 2011).
myoma (1 paper, 2015). "Thus, it can be inferred that CAV1 in the myoma model is expected to originate from the cell lines cultured in this assay." (PMID 25633184, 2015). "First, we investigated CAV1 expression in HSC-3 cell extracts in normoxia as well as in hypoxic (1%O2) and hypoxia-mimicking (CoCl2) conditions, similarly to what had been investigated in the myoma model." (PMID 25633184, 2015). "We found CAV1 expression to be higher in the TME-like myoma environment compared to the cultured cancer cells, similar to the TSCC samples, even when severe hypoxic conditions were further induced in the myoma assays." (PMID 25633184, 2015). "In addition, since the same changes were seen in both normoxic and hypoxic conditions, it is proposed that hypoxia did not change the distribution of CAV1, given that the myoma model is characterized by an in-built potential for a hypoxic environment." (PMID 25633184, 2015).
myotonic dystrophy (1 paper, 2015). An inherited progressive disorder affecting the muscles. "Together, these findings strongly implicate altered calcium signaling and in particular overexpression of the embryonic splice variant CaV1.1e in mature muscles in the pathophysiology of myotonic dystrophy." (PMID 25762319, 2015). "Therefore, use of clinically approved calcium antagonists may be of therapeutic use in the treatment of myotonic dystrophy, provided the CaV1.1e splice variant is sensitive to L-type channel blockers." (PMID 25762319, 2015).
nephrotic syndrome (1 paper, 2023). A collection of symptoms that include severe edema, proteinuria, and hypoalbuminemia; it is indicative of renal dysfunction. "It thus indicates YBT exerts therapeutic effects on the edema of nephrotic syndrome, as it improves the hyperpermeability of renal microvasculature, and that YBT is engaged in the regulation of Cav-1/eNOS pathway-mediated endothelial function." (PMID 37229256, 2023).
Niemann-Pick disease (1 paper, 2016). A group of inherited, severe metabolic disorders in which sphingomyelin accumulates in lysosomes in cells. "The genes contributing to these GO pathways in the DILGOM sample were ATP-binding cassette, sub-family G, member 1 (ABCG1), caveolin 1 (CAV1), Niemann-Pick disease, type C1 (NPC1), and Niemann-Pick disease, type C1, gene-like 1 (NPC1L1), while in the experimental SR study they were ABCA1 and NPC1." (PMID 27102866, 2016).
ocular tumors (1 paper, 2025). "This discrepancy highlights the possibility of post-transcriptional or post-translational regulation and underscores the need to assess both transcript and protein levels to understand Cav-1 biology in ocular tumors." (PMID 41374987, 2025). "Integration with public datasets highlights CAV1 and GIPC1 as adverse survival correlates in UM and positions LRP2/CUBN/DAB2IP dysregulation as features of ocular tumor biology, nominating candidate biomarkers and mechanistic targets." (PMID 41374987, 2025). "Collectively, Megalin–Cubilin endocytosis, CAV1-mediated membrane signaling, and adaptor/tumor-suppressor nodes (GIPC1, DAB2IP) define axes that may govern differentiation, metabolic supply, and invasion in ocular tumors." (PMID 41374987, 2025).
odontogenic tumor (1 paper, 2021). "One study reported variable caveolin-1 positivity in the epithelial lining of the primordial odontogenic tumor, associating its expression with different stages of cellular differentiation and tumoral transformation." (PMID 33037799, 2021). "There are only two immunohistochemical studies reporting the expression of caveolin-1 in odontogenic tumors and cysts." (PMID 33037799, 2021). "The expression patterns and roles of caveolin-1 in the oral epithelium and in embryonic and odontogenic tumor tissues are still unclear." (PMID 33037799, 2021).
oncocytomas (1 paper, 2012). "Additional markers such as Caveolin-1, which was shown to be positive in 87% of chromophobe RCCs (20 of 23) and 0% of oncocytomas (0 of 8) and MOC-31, which was positive in 96% (22 of 23) of chromophobe RCCs and only 25% (2 of 8) of oncocytomas may also provide clinically important data." (PMID 22973552, 2012).
Pain (1 paper, 2022). An unpleasant sensory and emotional experience associated with actual or potential tissue damage, or described in terms of such damage. "Caveolin-1 (CAV-1) is involved in neuropathic pain, and adenosine monophosphate (AMP)-exchange protein directly activated by cAMP1 (EPAC-1) is a potential therapeutic target for chronic pain." (PMID 35958678, 2022).
pancreatic disease (1 paper, 2025). "In malignant contexts, β-HB has been demonstrated to facilitate ferroptotic cell death by inhibiting caveolin-1 (CAV1) production, hence illustrating its dual regulatory role in pancreatic disease." (PMID 41228299, 2025).
papillary adenocarcinoma (1 paper, 2008). A morphologic variant of adenocarcinoma. "Significantly (P < 0.05) higher levels of Cav-1 and Cav-2 expression were detected in the carcinoma tumors compared to their papillary adenocarcinoma counterparts (2.8- and 3.8-fold, respectively)." (PMID 18811984, 2008). "Cav-1 is also involved in cell adhesion and was expressed at higher levels in the carcinoma tumors than in the papillary adenocarcinomas." (PMID 18811984, 2008).
parasite infection (1 paper, 2020). "Thus, whereas MEFs lacking Cav1 are partially less susceptible than WT MEFs to T. cruzi infection, deficiency in both Cav1 and EndoA2 strongly impairs the cells' ability to survive during the parasite infection process." (PMID 33093240, 2020).
Parkinsonism (1 paper, 2019). Characteristic neurologic anomaly resulting from degeneration of dopamine-generating cells in the substantia nigra, a region of the midbrain, characterized clinically by shaking, rigidity, slowness of movement and difficulty with walking and gait. "We, therefore studied the role of CaV1.342 (full-length channel) and CaV1.342A in mouse SNpc in PD pathogenesis by quantifying mRNA levels of CaV1.342 and CaV1.342A in SNpc and followed the change in their levels in MPTP induced parkinsonism mouse model." (PMID 32009942, 2019).
penile cancer (1 paper, 2021). A primary or metastatic malignant neoplasm that affects the penis. "Upon penile cancer progression, significantly increased CAV1-levels were determined within the malignant epithelium, whereas within the tumor stroma, namely the fibroblastic tumor compartment harboring activated and/or cancer associated fibroblasts, CAV1 levels significantly decline." (PMID 33868995, 2021). "However, the clinical significance of CAV1 expression in penile cancer remains largely unknown." (PMID 33868995, 2021).
penile tumor (1 paper, 2021). "Of note, a significant lower CAV1 content in malignant epithelial cells as determined by significant lower CAV1 scores was present in p16 expressing penile tumors." (PMID 33868995, 2021). "At the same time, no reports considering the role of CAV1 in penile tumors were available." (PMID 33868995, 2021).
periodontal disease (1 paper, 2025). "This highlights the complex interaction between EMMPRIN and Cav-1 in periodontal disease progression and underscores the potential of periodontal therapy to restore a balanced expression of these markers." (PMID 40075856, 2025). "EMMPRIN appears to facilitate tissue destruction in periodontal disease, whereas Cav-1 helps reduce inflammation." (PMID 40075856, 2025). "EMMPRIN and Caveolin-1 (Cav-1) have been identified as significant contributors to the pathogenesis of periodontal disease, yet there is limited understanding of how they interact and influence periodontal inflammation." (PMID 40075856, 2025). "Thus, the co-localization of EMMPRIN and caveolin-1 in periodontal tissues may play a crucial role in the pathogenesis of periodontal disease." (PMID 40075856, 2025).
plague (1 paper, 2016). Plague is a severe bacterial infection caused by the gram-negative bacterium Yersinia pestis. "Other experiments revealed that deficiency of Cav-1 appeared atheroprotective and decreased plague area." (PMID 27119011, 2016).
polycystic ovary syndrome (1 paper, 2019). A disorder that manifests as multiple cysts on the ovaries. "Decreased phosphorylation of CAV1 at residue Y14 was related to the insulin-resistant state in endometrial tissue of polycystic ovary syndrome patients." (PMID 31442208, 2019).
Polyuria (1 paper, 2018). An increased rate of urine production. "Steady state polyuria and urinary salt loss in our Cav1−/− mice suggest that Cav1 may further be involved in the renal reabsorption of salt and water." (PMID 29323234, 2018). "Cav1 disruption may therefore increase NO bioavailability, which in turn may contribute to the observed polyuria in the Cav1−/− mice." (PMID 29323234, 2018).
prediabetes (1 paper, 2024). "The downregulation of caveolin-1 in the prediabetes group compared to normoglycemic individuals in our study could imply insufficient exercise among our patients and a possible transition from normoglycemia to a prediabetic state, which could impair caveolae function and insulin signaling." (PMID 39085321, 2024).
pregnancy disorder (1 paper, 2022). A disorder that is related to pregnancy. "In contrast, a direct interaction between hAQP3 and the Caveolin-1 complex could be detected in extravillous trophoblast cells and functional data suggest that an altered AQP3–Caveolin-1 interaction may result in pregnancy disorders." (PMID 36077012, 2022).
Premature ovarian insufficiency (1 paper, 2021). Amenorrhea due to loss of ovarian function before the age of 40. "It has also been shown that downregulation of CAV-1 gene expression in female ovaries pathway affects the Notch2 signaling and causes a decrease in Leucine-rich repeat containing G protein-coupled receptor 5 (Lgr5) leading to POI (premature ovarian insufficiency)." (PMID 34827207, 2021).
promyelocytic leukemia (1 paper, 2007). "Tyrosine14 phosphorylation of caveolin-1 was found to be associated with apoptosis in the human promyelocytic leukemia cell line HL-60 after etoposide induction, indicating phosphorylation of caveolin-1 tyrosine may play a role in apoptosis." (PMID 17331262, 2007).
psychostimulant addiction (1 paper, 2021). "Our results demonstrate that Cav1 expression and knockdown driven striatal plasticity assist with modulating addiction to drug and nondrug rewards, and inspire new strategies to reduce psychostimulant addiction." (PMID 34360984, 2021).
retinal vascular disorder (1 paper, 2023). Retinal damage resulting from diminished blood flow/oxygenation due to abnormalities of the retinal vessels. "The preservation of sufficient Cav-1 levels and its potential downstream signaling pathways may serve as a target in treating retinal vascular disorders." (PMID 37923999, 2023).